TXN (thioredoxin)
Diseases named in the same sentence as TXN in open-access papers (continued):
Sharing a sentence is not in itself a finding about the gene and the disease.
lymphoma (7 papers, 2009 to 2025). A malignant (clonal) proliferation of B- lymphocytes or T- lymphocytes which involves the lymph nodes, bone marrow and/or extranodal sites. "The cross-sectional pathological analysis (22–25 months old) showed that Tg(TXN)+/0 mice had a significantly higher severity of lymphoma and more tumor burden than WT mice, which was associated with the suppression of the apoptosis signal-regulating kinase 1 (ASK1) pathway." (PMID 30370017, 2018). "The cross-sectional pathological analysis of old mice (22–25 months old) indicates that the Tg(TXN)+/0 mice had a significantly higher severity of lymphoma and more tumor burden than WT mice." (PMID 30370017, 2018). "The cross-sectional pathology showed that the old (22–25 months) Tg(TXN)+/0 mice had a significantly higher severity of lymphoma and more tumor burden than WT mice, which was correlated with the suppression of the ASK1 pathway." (PMID 30370017, 2018). "However, the Tg(TXN)+/0 mice had a significantly higher severity of lymphoma than WT mice (p = 0.0001)." (PMID 30370017, 2018). "The accelerated tumor development in old mice in this study is also consistent in part with our previous study with Tg(act-TXN)+/0 mice, in which end-of-life pathology of Tg(act-TXN)+/0 mice had a slightly higher incidence of fatal lymphoma compared to WT mice." (PMID 30370017, 2018). "In addition, the Tg(act-TXN)+/0 mice showed a slightly higher incidence of cancer, especially lymphoma, compared to WT mice." (PMID 30370017, 2018). "Therefore, the continuous overexpression of Trx1 plays more important roles in tumor development, especially lymphoma than other age-related diseases in Tg(TXN)+/0 mice." (PMID 30370017, 2018). "When we measured GSH/GSSG ratio and activity of thioredoxin in EL-4 cells, the ratio of GSH to GSSG was significantly higher in EL-4 lymphoma cells as compared to normal lymphocytes under basal conditions." (PMID 23776571, 2013). "Employing a pharmacological screen, we demonstrate how targeting PRPS1 or PRPS2 elicits opposing sensitivity or resistance, respectively, to chemotherapeutic agents affecting the thioredoxin and glutathione network, thus providing a therapeutic blueprint for treating MYC-driven lymphomas." (PMID 39868212, 2025). "It is known that exposure of primary cells under hypoxic conditions to normoxia induces the expression of redox genes, particularly thioredoxin, and consistent with this, established EBV-positive lymphoma lines grown in vitro express considerably higher levels of thioredoxin than primary B-cells." (PMID 19521517, 2009).
periodontitis (7 papers, 2015 to 2025). An acute or chronic inflammatory process that affects the tissues that surround and support the teeth. "In one oxidative stress–focused analysis, hub genes including CASP3, IL-1β, and TXN were shown to discriminate periodontitis subtypes with immune-correlated expression profiles." (PMID 40981157, 2025). "Albumin and Thioredoxin were up-regulated in periodontitis cases, while Cystatins (mainly S, SA, SN) and Lactotransferrin were down-regulated." (PMID 36355174, 2022). "Recently, proteomic analysis of the saliva of Grade B Stage 2 periodontitis patients revealed that histatin-1, proline-rich phosphoprotein, thioredoxin, and cystatin-SA were increased in Grade B Stage 2 periodontitis." (PMID 35330371, 2022). "We discovered 3 periodontitis-associated genes (CASP3, IL-1β, and TXN)." (PMID 37475857, 2023). "As previously reported, ROS induced the activation of NLRP3 by causing thioredoxin (TRX)-interacting protein (TXNIP) to dissociate from thioredoxin, which may be associated with periodontitis." (PMID 28690552, 2017). "In addition, a study in diabetic patients with periodontitis showed that DNA methylation was one of the regulators of proteins interacting with thioredoxin, highlighting possible new target therapies for type 2 diabetes and a reflected impact in the control of diabetes-associated periodontitis." (PMID 36430182, 2022).
atherosclerosis (6 papers, 2011 to 2022). A disease characterized by the build-up of fatty material and calcium deposition in the arterial wall resulting in partial or complete occlusion of the arterial lumen. "In this review, we place particular emphasis on the thioredoxin system by providing updated information about its implication in atherosclerosis." (PMID 35008500, 2021). "Of particular interest, pathway enrichment analysis of the 34 common gene associated DMRs revealed epigenetic impairment of NRF2 oxidative stress (SOD2), DNA repair (BRCA1), thioredoxin (TXNRD1) and inflammatory pathways (MIF, PLA2G4D) in atherosclerosis conditions." (PMID 28698603, 2017).
Cerebral ischemia (6 papers, 2008 to 2023). Restriction of arterial blood supply to the brain associated with insufficient oxygenation to support the metabolic requirements of the tissue. "Experimental results show that intravenous administration of recombinant human thioredoxin and overexpression of Trx1 in transgenic mice confer resistance to ROS-induced cell death, ultimately decreasing brain damage in cerebral ischemia models." (PMID 36737785, 2023).
chronic obstructive pulmonary disease (6 papers, 2013 to 2024). A chronic and progressive lung disorder characterized by the loss of elasticity of the bronchial tree and the air sacs, destruction of the air sacs wall, thickening of the bronchial wall, and mucous accumulation in the bronchial tree. "In addition, thioredoxin has been considered a promising future target for the treatment of digestive tract irritation, chronic obstructive pulmonary disease, and some allergic diseases such as allergic asthma, AR, food allergy, and contact dermatitis." (PMID 39403377, 2024).
colon carcinoma (6 papers, 2005 to 2024). "For instance, if COX2 is mentioned in PubMed as being associated with colon cancer 510 times but thioredoxin is associated with colon cancer only once, then one is more likely to have more confidence in the COX2-colon cancer association." (PMID 23300405, 2012). "Correlative evidence suggests the involvement of principally and commonly modulated pathways of thioredoxin, superoxide dismutase, and glutathione in breast, lung, pancreatic, prostate, and colon cancers." (PMID 39180118, 2024). "Taken together, our data strongly indicate that SOCS1 antagonizes EMT by suppressing Src activity, leading to thioredoxin expression and down-regulation of ROS levels in colon cancer cells." (PMID 27613835, 2016). "In order to elucidate the mechanisms for the reciprocal regulation of thioredoxin and ROS by SOCS1 to attenuate EMT in colon cancer cells, we have investigated the function of Src as a mediator of SOCS1 action." (PMID 27613835, 2016). "In summary, we have shown that ROS signal potentially induces EMT in colon cancer cells through Src activation and that SOCS1-induced inhibition of Src activity leads to the up-regulation of thioredoxin via Nrf-2, thereby inhibiting EMT." (PMID 27613835, 2016). "Thioredoxin transfection has been shown to increase HIF1α transactivation activity and the protein products of hypoxia-responsive genes such as VEGF and nitric-oxide synthase in MCF7 breast and HT29 colon cancer cell lines under both aerobic and hypoxic conditions." (PMID 15655539, 2005). "Interestingly, we found that BSO significantly enhanced ESI-induced cell death in HCT116 and RKO cells via promoting generation of ROS, indicating that a combination therapy inhibiting both thioredoxin and GSH systems may become an effective way to treat colon cancer." (PMID 33072762, 2020).
glaucoma (6 papers, 2012 to 2024). Increased pressure in the eyeball due to obstruction of the outflow of aqueous humor. "Our analysis of retinal gene expression profiles of animal glaucoma models implicated the proteins of the thioredoxin (Trx) system in the elevated IOP-induced oxidative process." (PMID 35610341, 2022). "Several studies have confirmed that the overexpression of TXN increases RGC’s survival in treating glaucoma." (PMID 39408566, 2024). "Previous studies have reported the possible involvement of thioredoxin system dysregulation in the pathogenesis of glaucoma; thus, measurement of the thioredoxin level separately from the other thiol groups should be done in the future." (PMID 23189153, 2012). "In support, the overexpression of thioredoxin was reported to protect the RGCs from apoptosis after optic nerve axotomy in pharmacologically induced oxidative stress in an in-vitro and in-vivo animal model of glaucoma." (PMID 34408771, 2021). "Previous studies have reported that thioredoxin system dysregulation may be a factor in the pathogenesis of glaucoma." (PMID 26186651, 2015).
Hypertension (6 papers, 2011 to 2024). The presence of chronic increased pressure in the systemic arterial system. "In human, expression of thioredoxin systems generally increases in response to inflammation associated with hypertension and atherosclerotic plaques." (PMID 32210049, 2020). "Our results reveal that the response of the thioredoxin system depends on the model of hypertension." (PMID 30223427, 2018). "These are the first data indicating that the response of the thioredoxin heart system to hypertension, as well as chronic administration of URB597, in hypertensive rats depends on the type of hypertension." (PMID 30223427, 2018). "The TXN system is upregulated in high-stress oxidative conditions such as during hypertension episodes (while the GSH system is downregulated), however, this activation still seems insufficient for maintaining a normal redox status in these patients." (PMID 26329592, 2015). "Nevertheless, the response of the thioredoxin system depended on the model of hypertension." (PMID 30223427, 2018). "According to the observed changes in mRNA and the OS level, it can be hypothesized that the GSH system plays a larger role than the TXN system does in hypertension." (PMID 22016650, 2011).
ischemia (6 papers, 2012 to 2023). A hypoperfusion of the BLOOD through an organ or tissue caused by a PATHOLOGIC CONSTRICTION or obstruction of its BLOOD VESSELS, or an absence of BLOOD CIRCULATION. "The synthesis of thioredoxin is activated under oxidative stress-related conditions such as infections and ischemia, and under some chronic vascular disease such as hypertension and atherosclerosis as well." (PMID 31637257, 2019). "In accordance to previous reports, these findings are suggesting a protective role of extracellularly injected recombinant human thioredoxin on injury, for example in the case of neuronal cells induced by ischemia/reperfusion." (PMID 23236492, 2012). "Because recombinant thioredoxin has been shown to have neuroprotective effects both in vitro and in vivo, some authors have proposed it as a prospective option for the treatment of ischemia, where it has been evaluated and all its benefits have been observed." (PMID 37157915, 2023). "This compound also protects erythroblasts against oxidative stress by upregulating the expression of antioxidant molecules, glutathione peroxidase, and thioredoxin, and it also reverses ischemia-induced cardiomyocyte death through inhibiting ROS overgeneration." (PMID 23589720, 2013). "Similarly, in isolated hearts with ischemia/reperfusion injury, we also found that SOD-2 and thioredoxin were remarkably reduced in the left ventricle of rat hearts subjected to 30 min ischemia followed by 2 h reperfusion (n = 4, P < 0.01 vs. sham group)." (PMID 27819271, 2016). "Cardiac mitochondria can degrade H2O2 via the glutathione (GSH), thioredoxin (TRX), and catalase pathways, and, therefore, altered activity of these pathways could explain the difference in ROS production between control and ischemia mitochondria." (PMID 35867709, 2022). "However, similarly to thioredoxin, the elevation of nitrotyrosine level is probably the result of CAS-induced ischemia, but not the cause of CAS." (PMID 31637257, 2019).
malaria (6 papers, 2017 to 2023). Malaria is a serious and sometimes fatal disease caused by a parasite that commonly infects a certain type of mosquito which feeds on humans. "Malaria parasites lack catalase and glutathione peroxidase and therefore depend on their other glutathione and thioredoxin-dependent redox relays." (PMID 35434650, 2022). "The malaria parasite possesses two major antioxidant systems, the glutathione system and the thioredoxin system, to deal with these oxidative stresses." (PMID 32670896, 2020). "The glutathione and thioredoxin systems may provide a way for malaria parasites to maintain redox homeostasis and antioxidant defense, considering that P. falciparum lacks glutathione peroxidase and catalase." (PMID 29128848, 2017).
Obesity (6 papers, 2013 to 2024). Accumulation of substantial excess body fat. "TXNIP, originally characterized as a thioredoxin (TRX)‐binding protein that regulates the antioxidant function of TRX 78, is implicated in obesity and inflammation." (PMID 28857469, 2018). "Molecular pathway analysis of LRRK2 reveals direct links between LRRK2 and the thioredoxin system, which interacts with PRDX3, TXNIP and TXNRD1, proteins that are associated with nutrient sensing, adiposity and human obesity." (PMID 23799078, 2013). "However, this is the first report in which it was found that T allele is a protective factor against obesity and we suggest that TXNIP expression or function would be affected allowing TXN to exert its antioxidant action." (PMID 27274779, 2016).
asthma (5 papers, 2012 to 2024). "Thioredoxin (TRX) is a protein that regulates reactive oxidative metabolism and scavenges reacting oxygen species, which is implicated in the mechanism of asthma." (PMID 32467711, 2020). "A study of the suppressive effect of thioredoxin on airway inflammation using a mouse model of asthma showed that IL-13 and exotoxin production were significantly reduced in TRX-transgenic (TRX-Tg) mice, which reduced eosinophil recruitment and decreased mucus metaplasia." (PMID 39403377, 2024). "This hypothesis is further complemented by the M2 polarization profile (APOE, TXN, TGM2, STING1, NAMPT) enriched in this group, a dominant macrophage profile in high Th2-type asthma in humans and one known to activate the Th2 response with downstream eosinophilic infiltration and airway remodeling." (PMID 39594673, 2024). "Selenium exerts its chemopreventive effect through the glutathione and thioredoxin systems, while some investigations suggest protective effects against allergies, and asthma, the other studies could not find a correlation between selenium and asthma." (PMID 23530936, 2013).
autoimmune disease (5 papers, 2018 to 2025). A disorder resulting from loss of function or tissue destruction of an organ or multiple organs, arising from humoral or cellular immune responses of the individual to their own tissue constituents. "We are currently evaluating the homologous human fusion protein of the mouse thioredoxin/IL-2 fusion protein PDC as a potential drug candidate to treat several autoimmune diseases and, potentially, allergic asthma." (PMID 36569931, 2022). "Another key antioxidant system in DN is thioredoxin (Trx) which is localized in the mitochondria and the cytoplasm, protects cells from oxidative stress through its disulfide reductase activity, and has as a reciprocal role in disease pathogenesis: autoimmune diseases and cancer." (PMID 31998774, 2020). "As such, we envision that the combination of DMF and pharmacological approaches that target TXN system may represent a more effective strategy than DMF alone for treating T cell-mediated inflammation and autoimmune disease." (PMID 30198844, 2018).
bladder cancer (5 papers, 2018 to 2025). "It has been found that the reduced expression of thioredoxin can sensitize bladder cancer T24 cells to doxorubicin, mitomycin C, etoposide, hydrogen peroxide, and UV irradiation." (PMID 39860164, 2025). "Inducing ROS-mediated paraptosis to suppress the growth of DDP-resistant bladder cancer by targeting thioredoxin and glutathione systems." (PMID 38239395, 2023). "Another in vivo study showed that morbidiolide B induces ROS-mediated apoptosis in bladder cancer cells by targeting thioredoxin and glutathione systems." (PMID 35855902, 2022). "Similarly, WFA upregulates the mRNA expression of antioxidant genes (NFE2L2, CAT, SOD1, TXN, GSR, NQO1, and HMOX1) in bladder cancer cells associated with oxidative stress generation." (PMID 34209212, 2021).
COVID-19 (5 papers, 2020 to 2025). A disease caused by infection with severe acute respiratory syndrome coronavirus 2. "Utilizing violin plots, we observed that the alteration trends in the expression of hub genes within the validation dataset mirrored those in GSM172114, confirming the heightened expression of SAT1, MTF1, and TXN in the COVID-19-induced ARDS group." (PMID 39170609, 2024). "Other scRNA sequencing results also support the conclusion that SAT1 and TXN are elevated in severe COVID-19 patients." (PMID 39170609, 2024). "Both thioredoxin (Trx) protein level and thioredoxin reductase (TrxR) activity of the thioredoxin system (Trx and TrxR) were significantly elevated in the plasma of COVID-19 patients compared to healthy subjects." (PMID 36014561, 2022). "Therefore, the bidirectional nature of redox changes observed in the bodies of people with COVID-19, including survivors and those deceased, with respect to the thioredoxin-glutathione system, confirms the possibility of an atypical host response to this infection." (PMID 36014561, 2022). "To date, no reproducible associations between TXN/TXNRD germline variants and COVID-19 severity have been established." (PMID 41209585, 2025).
gastric cancer (5 papers, 2016 to 2025). A primary or metastatic malignant neoplasm involving the stomach. "The discovery of B19-TrxR1 interaction provides deep insight into the understanding of how B19 acts in vivo as well as developing the novel thioredoxin system-targeting small molecules for gastric cancer chemotherapy." (PMID 26919094, 2016). "TXN and TXNRD1 expression levels significantly increased in tumor tissue samples from colorectal, lung, and stomach cancers." (PMID 39744566, 2025). "The hub proteins identified, CAT, PLEKHA4, HSP90AB1, TXN, EEF2, H6PD, and PDIA3, may play important roles in the treatment of gastric cancer using nintedanib." (PMID 38406279, 2024).
Insulin resistance (5 papers, 2018 to 2025). Increased resistance towards insulin, that is, diminished effectiveness of insulin in reducing blood glucose levels. "We found that haemoglobin A1c, fasting blood glucose, fasting insulin, homeostasis model assessment of insulin resistance and thioredoxin interaction protein were enhanced, while HOMA-β was reduced with the decrease of 25(OH)D concentration." (PMID 36874363, 2023). "Recent studies showed that afamin can bind to thioredoxin, leading to oxidative stress and, consequently, to insulin resistance." (PMID 34803906, 2021). "Using cultured 3T3-L1 adipocytes, we established a model of physiologically-derived oxidative stress by inhibiting the cycling of glutathione and thioredoxin, which induced insulin resistance as measured by impaired insulin-stimulated 2-deoxyglucose uptake." (PMID 29379070, 2018).